PRL (prolactin)
Diseases named in the same sentence as PRL in open-access papers (continued):
Sharing a sentence is not in itself a finding about the gene and the disease.
breast cancer (continued). "Our studies may provide insights for therapeutic approaches that will mitigate the transcription/expression of PRLR and its participation in breast cancer progression fueled by E2 and PRL via their cognate receptors." (PMID 36187116, 2022). "However, multiple recent studies have reported PRLR protein expression in ER+, HER2+ and triple negative (TNBC) breast cancers, in sharp contrast to the epidemiologic link between PRL and development of only ER+ breast cancers." (PMID 35784527, 2022). "Extension of these studies of the effect of ECM characteristics on PRL signals to other breast cancer subtypes may further resolve some of the apparently contradictory reports." (PMID 35784527, 2022). "Well-characterized breast cancer cell lines modeling different breast cancer subtypes have been extensively studied in vitro to understand the outcomes of PRL actions, and to dissect its signals and mechanisms of interaction with other factors; these reports will not be further reviewed here." (PMID 35784527, 2022). "We have also analyzed PRL protein and mRNA levels in breast cancer cases." (PMID 36157462, 2022). "These actions of PRL on breast epithelia and potentially on other stromal cells could support development of breast cancers." (PMID 35784527, 2022). "PRL/PRLR is expressed in 95% of mammary tumors and 60% of male breast carcinomas." (PMID 36187116, 2022). "In this study, the correlation between PRL and breast cancer endocrine resistance was reviewed." (PMID 34651424, 2021). "Activation of PRLR promotes mammary tumor development in transgenic mice overexpressing PRL gene." (PMID 34572912, 2021). "Estrogen can also increase PRL-activated Stat5 activity in breast cancer cells." (PMID 34572912, 2021). "PRL promotes cell motility in several breast cancer cell lines mediated through EGF." (PMID 34572912, 2021). "For example, while epidemiologic studies demonstrate a positive correlation between circulating PRL concentration and breast cancer risk, patients with hyperprolactinemia are overall not at an increased risk for breast cancer." (PMID 33772010, 2021). "Also, restoring and activating the PRL pathway was found to supress breast cancer stem-like cell (BCSC) subpopulations CD44+/CD24− and ALDH+ and reduced breast tumorigenesis in vitro and in vivo." (PMID 33446633, 2021). "PRL is the receptor for mammotrophic hormone, which is also expressed in many breast cancers." (PMID 34034721, 2021). "In the future, the relevance of PRL and molecular subtypes of breast cancer requires further study." (PMID 34651424, 2021). "In breast cancer cells, prolactin promotes actin regulation, thus enhancing cell movement." (PMID 34203892, 2021). "The PRL/PRLR pathway has been studied for decades because of its etiological role in breast cancer." (PMID 34077462, 2021). "Recombinant human prolactin antagonists are potential drugs that inhibit target prolactin receptors in dopamine-resistant prolactinomas, breast cancer, prostate cancer, and ovary cancer, in all cases where autocrine PRL acts as growth promoting agent, or even for pain release and to avoid hair loss." (PMID 33905023, 2021). "Restraint stress facilitates the development of dimethyl benzanthracene (DMBA) induced mammary tumors by releasing β-endorphin and prolactin, However, naltrexone, an opioid receptor antagonist, exerts a beneficial effect by opposing the effect of β-endorphin on prolactin release in stressed animals." (PMID 34988010, 2021). "The prolactin pathway, known as a hormone involved in normal breast development and lactation, has been long demonstrated to be involved in the progression of human breast cancer." (PMID 33475963, 2021). "Prolactin's (PRL) role in breast cancer pathogenesis has been gaining increasing attention." (PMID 34651424, 2021).
breast cancer (continued). "In the same line, prolactin also enhances Insulin growth factor 1 (IGF1)-induced phosphorylation of IGF1-receptor increasing its AKT and ERK1/2 downstream signaling associated with proliferation, survival and invasion of breast cancer cells." (PMID 34294140, 2021). "Emerging evidence also support prometastatic roles of PRL for ER+ breast cancer." (PMID 34524841, 2021). "Together, these findings highlight the complex nature of PRL role in breast cancer." (PMID 33446633, 2021). "PRL stimulates breast cancer cell proliferation through HER2 expression." (PMID 34099636, 2021). "Our understanding of the role of PRL in breast cancer remains however incomplete." (PMID 33446633, 2021). "Therefore, keep exploring the role of PRL and its targeted therapies in the mechanism of endocrine therapy resistance in breast cancer plays a significant role in its becoming a method to overcome endocrine therapy resistance clinically." (PMID 34651424, 2021). "The potential prolactin link with breast cancer remains controversial because women with schizophrenia have many other risk factors that contribute to an elevated rate of breast cancer—low parity and breastfeeding, obesity, high rate of smoking, caffeine, and substance abuse." (PMID 34575706, 2021). "They measured PRL levels <10 and ≥10 years before the diagnosis of breast cancer." (PMID 34651424, 2021). "The pituitary hormone prolactin (PRL) is essential for proliferative expansion of normal differentiated breast epithelial cells, promotes malignant ER+ mammary tumors in rodents, and is a risk factor for ER+ breast cancer in women." (PMID 34524841, 2021). "Epidemiological studies have established the involvement of circulating PRL in breast cancer (BC)." (PMID 34071395, 2021). "It has previously been suggested that antipsychotics, via their effects on prolactin levels, may influence breast cancer prognosis." (PMID 32831062, 2020). "Here, we tested the hypothesis that the PR-B and PR-A isoforms differentially modify the ability of prolactin to transcriptionally regulate the expression of the FASN gene in PR+ breast cancer cells." (PMID 33335078, 2020). "To evaluate the relevance of PR isoform expression and ratio on the regulatory activity of prolactin for FASN gene expression, we used the PR-A/PR-B-positive (T47Dco) and PR-null (T47D-Y) variants of the estrogen receptor (ER)/PR-positive breast cancer cell line T47D." (PMID 33335078, 2020). "In addition, NEK3 has been described as having a role in PRL-mediated cytoskeletal re-organization and breast cancer cell migration and invasion." (PMID 32294979, 2020). "Prolactin promotes breast cancer cell migration through actin cytoskeleton remodeling." (PMID 33299802, 2020). "Many antipsychotics elevate prolactin, a hormone implicated in breast cancer aetiology however no studies have investigated antipsychotic use in patients with breast cancer." (PMID 32831062, 2020). "Because AKT is rapidly repressed in response to C75-induced blockade of FASN activity, our findings suggest a positive feedback regulation between FASN and autocrine prolactin expression via AKT-driven activation of the PRLR/JAK/STAT5 pathways in PR+ breast cancer cells." (PMID 33335078, 2020). "We first assessed how PR-B and PR-A isoforms could modify the ability of prolactin to regulate the expression of the FASN gene in PR+ breast cancer cells." (PMID 33335078, 2020). "The frequent secretory activity of rabbit mammary tumors may suggest an influence of prolactin on tumorigenesis." (PMID 31581718, 2019). "Although there are not many studies that demonstrate the participation of estrogen and prolactin in cervical carcinogenesis, these have also been related to the development of mammary tumors and their receptors are an important therapeutic target in breast cancer." (PMID 31507337, 2019).
breast cancer (continued). "The protection gained from breastfeeding could also be due to long-term endogenous hormonal change, i.e., decreased estrogen and increased prolactin levels, thus, inhibiting initiation and growth of breast-cancer cells." (PMID 30832620, 2019). "In addition to CEA and CYFRA21, we sought to discover more new and stable serum-based biomarkers such as prolactin (PRL) in breast cancer." (PMID 30555348, 2018). "It remains unclear whether this reflects a true effect of chronic prolactin overexposure on breast cancer progression, or, perhaps more likely, if issues with confounding by indication are exacerbated among patients with long-term depression." (PMID 29351761, 2018). "Experimental data suggest that prolactin and progesterone are involved in breast cancer aetiology by promoting the proliferation and differentiation of mammary epithelial cells, however, the number of studies in this regard is limited and there is insufficient evidence." (PMID 30572623, 2018). "ER-PR-K5+ luminal breast cancer cell populations, termed ‘luminobasal’ cells exhibiting enhanced progenitor properties can be induced by progestins, glucocorticoids, as well as mineralocorticoids and blocked by anti-progestins and prolactin." (PMID 28147318, 2017). "We initiated studies to determine whether endogenous PRL action in breast cancer cells is required for E2 induced increase in PRLR gene expression." (PMID 28423697, 2017). "Among which, ESR2 was shown to be involved in the estrogen and prolactin signaling pathways and may take a significant role in the effect of germacrone, curdione, and furanodiene in the treatment of breast cancers and should be studied in animal models." (PMID 29138518, 2017). "To explore how prolactin might reduce expression of p21 mRNA, we performed a miRNA microarray in T-47D breast cancer cells." (PMID 28422740, 2017). "We have previously shown that characteristics of the collagen ECM alter the spectrum of PRL-induced signals with behavioral consequences in human breast cancer cells in vitro: stiff/dense matrices reduce signals to STAT5, while increasing signals through ERK1/2." (PMID 28103936, 2017). "Interestingly, mice genetically engineered to express human PRL appear to increase successful transplantations of human primary ERα + breast cancer." (PMID 28103936, 2017). "To investigate whether tyrosine phosphatases regulate PRL/pTyr-PAK1-dependent T47D breast cancer cell migration, we examined migration of T47D clones in the presence and absence of PRL and Na3VO4 for 48 h." (PMID 27542844, 2016). "Thus, our current data on pTyr-PAK1 regulation of FAK phosphorylation bring insight into the mechanism of PRL-stimulated motility of breast cancer cells." (PMID 27542844, 2016). "Importantly, PRL has been noted as a chemoattractant for breast cancer cells and augments tumor metastasis in nude mice." (PMID 27542844, 2016). "There is mounting evidence that PRL plays a significant role in breast cancer." (PMID 27542844, 2016). "PRL signaling is complex, although it is clear that PRL could have an important impact on breast cancer bone metastases." (PMID 27782069, 2016). "Furthermore, using both mammary epithelial cells and human breast cancer cells we showed that PRL blocks growth factor-induced mammary cell proliferation and viability of breast cancer cells." (PMID 27480353, 2016). "Furthermore, we provide in vivo evidence that PRL-induced pTyr-PAK1 increases breast cancer cell metastasis." (PMID 27542844, 2016). "Finally, we demonstrate for the first time that tyrosyl phosphorylation of PAK1 by PRL increases breast cancer cell metastasis in vivo." (PMID 27542844, 2016). "Thus, this review will focus on the role of prolactin in breast development, bone homeostasis and in breast cancer to bone metastases, covering the molecular aspects of the vicious cycle." (PMID 27782069, 2016).
breast cancer (continued). "Furthermore, PRLR can be used as a predictive marker for the possible use of PRL as a pro-differentiation therapy in breast cancer." (PMID 27480353, 2016). "Notably, a previous study has shown that exogenous administration of prolactin strongly increases the likelihood of mammary tumor formation, and, consistently, suppression of prolactin levels exerts an opposite effect in animal models." (PMID 27184120, 2016). "The role of prolactin on breast cancer development and progression is debated." (PMID 26733941, 2015). "However, PRL-activated SFKs mediate pro-tumorigenic signals and proliferation in breast cancer cell lines cultured on plastic." (PMID 25607819, 2015). "Previous evidence indicates that breast cancer cell motility is related to the abundance of PRL and PRLR transcripts, therefore suggesting the hypothesis that PRL signaling may have a role in this phenomenon." (PMID 26733941, 2015). "Notably, a genetically engineered prolactin-humanized mouse expressing physiological levels of human prolactin demonstrated a greatly improved take rate for ER-positive luminal breast cancers, which were found to be more responsive to tamoxifen." (PMID 25849559, 2015). "Moreover, they display striking differences in transcriptomes and resemblance to clinical breast cancer subtypes upon over expression of the PRL mediator, ELF5." (PMID 25607819, 2015). "Cancer development related to PRL, is mainly described in breast cancer." (PMID 26346346, 2015). "Lowering PRL serum levels by oral application of the dopamine receptor agonist cabergoline reduced the size of certain mammary lesions in 25 % of clinically pseudopregnant dogs presenting with mammary tumors." (PMID 26370564, 2015). "PRL effects on breast cancer are mediated by interaction with its receptor (PRLR), a member of the cytokine receptor superfamily, characterized by a tripartite structure: an extracellular ligand-binding domain, a short transmembrane domain, and an intracellular domain." (PMID 26733941, 2015). "However, several studies conducted in lymphocytes, endometrial stromal cells, and breast cancer cells provide an overview of PRL transcription in peripheral tissues." (PMID 25717285, 2015). "Consequently, the autocrine/paracrine loop of mammary PRL-PRLR complex contributing to human breast cancer development has also been implied for the dog." (PMID 26370564, 2015). "In breast cancer cells, SFKs triggered by PRL may generate pro-tumorigenic signals and stimulate cell motility." (PMID 26733941, 2015). "Prolactin is mitogenic, stimulates proliferation and suppresses apoptosis in breast and prostate cancer cells and is therefore important in the development of treatment-resistance in breast cancer cells." (PMID 25713759, 2015). "The second and larger study of 2,036 postmenopausal women who attended the Norwegian Breast Cancer Screening Program reported a significant interaction between SNP rs10946545 located 1.4kb 3′ of PRL and current use of estrogen-progesterone therapy for percent mammographic density (Pint = 0.0008)." (PMID 26275715, 2015). "Our findings elucidate one mechanism by which the desmoplastic response around advancing ERα+ breast cancers may permit estrogen and PRL to accelerate tumor growth and invasion, and resist endocrine therapy." (PMID 25607819, 2015). "In conclusion, prolactin regulates actin remodeling and enhances breast cancer cell movement." (PMID 26733941, 2015). "Although both elevated PRL levels and E2 supplementation are associated with increased mammographic density, the effect of these changes in the ECM on the actions of these hormones in ERα+ breast cancer is poorly understood." (PMID 25607819, 2015). "It is currently unclear whether PRL/PRLR signaling may turn into modifications that have an impact on breast cancer cell movement and possibly metastasis through the control of actin cytoskeleton rearrangement." (PMID 26733941, 2015).
breast cancer (continued). "The four new AKT1m transcripts were initially cloned from prolactin-responsive T47-D breast cancer cells, but the analyses of a larger panel of breast cancer cells as well as primary tumors show that expression of AKT1m is not restricted to luminal-type cancer cells." (PMID 24628780, 2014). "The potential relation between breastfeeding, prolactin and breast cancer is, however complex." (PMID 24708573, 2014). "A novel mechanism by which PRL may contribute to breast cancer progression is through its action on liver kinase 1 (LKB1)." (PMID 24913037, 2014). "Prolactin (PRL) is a key player in the development of mammary cancer." (PMID 25136563, 2014). "Also of special interest is the hormone prolactin, which has been found at reduced levels in the sera of parous women; coincidentally, prolactin-suppressing drugs have been shown to reduce mammary tumors." (PMID 25176219, 2014). "PRL is a potent mitogen that stimulates growth of rodent mammary tumors." (PMID 25193864, 2014). "Previous reports suggest that PRL can stimulate ER expression in some breast cancers." (PMID 25136563, 2014). "Taken together, our studies have demonstrated an increase in expression of PRLR receptors in breast cancer cells induced by endogenous PRL/PRLR action via STAT5 interaction with pERα and complex formation with Sp1/C/EBPβ at the PRLR promoter in the absence of estrogen." (PMID 25193864, 2014). "Gene products identified in the present study may facilitate ongoing deciphering of the pleiotropic effects of PRL on human breast cancer." (PMID 23758962, 2013). "Importantly, all nine PRL-induced transcripts were also partially suppressed by Jak1 knockdown, consistent with a significant role for Jak1 recruitment by PRL in breast cancer cells to maximize downstream signals." (PMID 23758962, 2013). "This global analysis identified and validated a panel of PRL-modulated transcripts in an ER-positive human breast cancer xenotransplant model, which may have value as markers of relapse-free and metastasis-free survival." (PMID 23758962, 2013). "Also, PRL treatment decreased induced cell death in breast cancer cells, from 28.7 to 18.3% in T47-D cells and from 30.6 to 21% in MCF-7 cells." (PMID 24148306, 2013). "Studies are ongoing to determine how modulation of these genes, including PTHrP, may mediate PRL effects in breast cancer." (PMID 23758962, 2013). "However, we have reported that in human breast cancer cell lines Jak1 is also recruited in a Jak2-dependent manner for maximal PRL-activation of Stat5 and other signaling mediators." (PMID 23758962, 2013). "This suggests that PRL has an important role in the cell survival of cervical and breast cancer." (PMID 24148306, 2013). "Due to the importance of PRL in breast cancer growth and differentiation, identifying genes regulated by the PRL-Stat5 pathway may provide new insights into the pleiotropic effects of PRL in breast cancer." (PMID 23758962, 2013). "The prolactin antagonist-ES fusion protein is a bifunctional protein, which inhibits both breast cancer cell proliferation and endothelial cell proliferation, exhibiting greater tumor inhibitory effects than prolactin antagonist and ES treated individually or in combination." (PMID 24128285, 2013). "Acidosis might affect prolactin-Stat5 signaling in breast cancer cells by mechanisms beyond disrupting prolactin receptor-ligand binding." (PMID 24004716, 2013). "Furthermore, whereas PRL alone exerted limited proliferative effect on T47D breast cancer cells in vitro, PRL enhanced E2-driven cell proliferation both on plastic and soft agar." (PMID 23758962, 2013). "On one hand, accumulating evidence suggests that PRL promotes breast cancer initiation and growth." (PMID 23758962, 2013). "Studies showed that PRL extends the lobular-alveolar cells survival on the lactating mammary gland, inhibiting apoptosis and stimulating the proliferation of many cell lines of breast cancer." (PMID 23317095, 2013).